GSK3B (glycogen synthase kinase 3 beta)
Diseases named in the same sentence as GSK3B in open-access papers (continued):
Sharing a sentence is not in itself a finding about the gene and the disease.
melanoma (continued). "Western blot analysis was conducted to assess the expression levels of p-GSK3β proteins in melanoma tissues (n = 6) and normal skin tissues (n = 6)." (PMID 41153674, 2025). "This study aimed to assess the expression of p-GSK3β in melanoma tissues and to evaluate the anti-melanoma efficacy of CA." (PMID 41153674, 2025). "Nobiletin, a natural product isolated from citrus peel, induces ferroptosis by modulating the GSK3β-mediated KEAP1/NRF2/HO-1 signaling pathway in human melanoma cells." (PMID 40331942, 2025). "Accordingly, this study was conducted to evaluate the expression of p-GSK3β in human melanoma tissues and to further elucidate the anticancer effects of CA on melanoma development." (PMID 41153674, 2025). "Evidence for its effects on the Wnt/β-catenin pathway remains relatively limited; however, melanoma cell studies showed that fisetin treatment reduces GSK3β phosphorylation, decreases β-catenin stability, and thereby suppresses the EMT phenotype." (PMID 41305575, 2025). "The precise involvement of GSK3β in melanoma pathogenesis remains less explored in comparison to its established roles in other malignancies." (PMID 41153674, 2025). "CA exposure decreased cell viability, triggered apoptosis, and elevated p-GSK3β levels in G361 melanoma cells." (PMID 41153674, 2025). "Emerging evidence indicates that GSK3β signaling fosters melanoma oncogenicity by modulating both N-cadherin expression and the dynamics of focal adhesion complexes." (PMID 41153674, 2025). "Western blot analysis further confirmed these findings, demonstrating that fisetin treatment elevated the expression of phosphorylated PI3K, Akt, and GSK3β by approximately 1.2-, 2-, and 2-fold, respectively, in melanoma cells." (PMID 41373883, 2025). "Our data provide a new concept of how a small GTPase, Rab7a affects cancer/melanoma hallmarks by controlling the activity of the endolysosomal cation channel TPC2 with effects on GSK3β degradation and thus β-Catenin and MITF levels." (PMID 39562548, 2024). "Here, the authors show that Rab7a enhances the activity of TPC2 to promote melanoma progression through the GSK3β/β-Catenin/MITF axis." (PMID 39562548, 2024). "β-Catenin is directly dependent on GSK3β phosphorylation for its degradation, and it is a known regulator of melanoma cell growth, with MITF as a critical downstream target." (PMID 39562548, 2024). "In another study, RA showed an inhibitory effect on melanoma cells via suppression of the ADAM17/EGFR/AKT/GSK3β axis resulting in the inhibition of melanoma cell proliferation, invasion, and migration." (PMID 37687080, 2023). "For example, although nobiletin alleviates AKI in UUO mice by suppressing ferroptosis, it induces ferroptosis in melanoma cells through the GSK3β-regulated Keap1/NRF2/HO-1 pathway." (PMID 37739961, 2023). "Previous studies have shown that BBR decreased the phosphorylation of PI3K/AKT, ERK, and GSK3β in B16F10 melanoma cells and inhibited the activation of EGFR in these tumors." (PMID 37170144, 2023). "RAS signaling and the effector ERK and PI3K/AKT/GSK-3β kinase cascades induce the phosphorylation, the stabilization and thus the activation of c-Myc in melanoma cells." (PMID 37377735, 2023). "This peptide inhibited the binding of CAGE to GSK3β, enhancing the sensitivity of melanoma cells to anti-cancer drugs." (PMID 36968022, 2023). "SERPINE2 promotes melanoma metastasis through the glycogen synthesis kinase 3β (GSK-3β) signaling pathway." (PMID 36505099, 2022). "The results of immunohistochemistry showed that GSK3β expression in the skin tissue of patients with melanoma was significantly reduced compared to that of normal skin tissue." (PMID 35350242, 2022). "SERPINE2 promoted melanoma metastasis through the glycogen synthesis kinase 3β (GSK-3β) signaling pathway in a mouse model." (PMID 35646893, 2022). "In our study, GSK3β expression level in the skin tissue of patients with melanoma was significantly decreased compared with that of normal skin." (PMID 35350242, 2022).
melanoma (continued). "Elraglusib (9-ING-41) is a specific small-molecule inhibitor of GSK-3β with clinical activity in patients with advanced cancers, including a patient with refractory melanoma whose response provided the rationale for the current study." (PMID 36104795, 2022). "Previous studies showed that PTPN11 was commonly active in human melanoma samples and played a carcinogenic role in melanoma by regulating Ras and GSK3β signaling pathways." (PMID 35802774, 2022). "In particular, p-GSK3β/S9 level was positively correlated with eEF2K and PD-L1 levels in these melanoma samples, which were consistent with our in vitro and in vivo studies." (PMID 35347072, 2022). "We then validated our findings in human melanoma samples through assessing protein expression level of p-GSK3β/S9." (PMID 35347072, 2022). "Collectively, our results demonstrated that the mechanism of nobiletin-induced ferroptosis involved regulation of the GSK3β-mediated Keap1/Nrf2/HO-1 signalling pathway in human melanoma cells." (PMID 35350242, 2022). "Here, we investigated the inhibitory effect of ITA and DMI on alpha-melanocyte-stimulating hormone (α-MSH)-induced MITF expression and the modulatory role of protein kinase B (AKT) and GSK3β in melanogenesis in B16F10 mouse melanoma cells." (PMID 35807430, 2022). "MAPK up-regulation blocks GSK3-β-dependent c-Myc degradation of asparagine-restricted melanoma cells." (PMID 36139919, 2022). "In this study, we investigated the anti-melanogenic effects of ITA and DMI on α-MSH-induced MITF expression and the modulatory role of AKT and GSK3β in melanogenesis in B16F10 mouse melanoma cells." (PMID 35807430, 2022). "Our results fully proved that RA played a role of protecting melanoma cells against malignant metastasis by inhibiting ADAM17/EGFR/AKT/GSK3β axis." (PMID 34224305, 2021). "Meanwhile, ABZ increased the accumulation of the active form of GSK-3β (pGSK-3β/Tyr216) in melanoma cells and changed the ratio of Tyr216/Ser9." (PMID 34966427, 2021). "In melanoma, microRNA miR-769 inhibits GSK3β activity during the tumor development process, which also indicates tumor-suppressing effects of GSK3." (PMID 32767962, 2021). "The PI3K/AKT pathway is frequently activated in the human melanoma cells and GSK-3β is inhibited as a result of phosphorylation of serine 9 by AKT." (PMID 32674468, 2020). "In another study, activation of A3AR using a selective agonist led to decreased proliferation of melanoma cells through inhibition of the phosphorylation or inactivation of GSK-3β that induced the phosphorylation or inactivation of β-catenin." (PMID 33187081, 2020). "Concordantly, Co-IP results illustrated that circ-GLI1 depletion strengthened the interaction of GSK3β with either GLI1 or β-catenin in melanoma cells." (PMID 32732916, 2020). "According to previous literature, the aerial part of Pueraria thunbergiana downgrades MITF by activating the Akt/GSK-3β signaling pathway in B16/F10 melanoma cells." (PMID 32245029, 2020). "It was demonstrated that cordycepin inhibited the proliferation of B16-BL6 mouse melanoma cells by stimulating adenosine A3 receptors followed by glycogen synthase kinase (GSK)-3β activation and cyclin D1 inhibition." (PMID 33172093, 2020). "A significant increase in melanoma apoptosis, compared to treatment with single agents, was obtained even by association of EZH2 inhibitor GSK126 with the GSK-3β inhibitor AR-014418, in agreement with the role of GSK-3β in NFATc2 regulation." (PMID 30710146, 2019). "Others have reported that pharmacological inhibition of GSK3B can induce apoptosis by sorafenib in melanoma cell lines and leukemic cells." (PMID 31108958, 2019). "As a further approach, we used zoledronic acid, a third generation biphosphonate with significant anti-melanoma activity that inhibits the GSK-3β-dependent NFATc2 nuclear stabilization pathway." (PMID 30710146, 2019).
melanoma (continued). "Of note, virally enforced over-expression of CA.GSK3β in melanoma cells also reduced their DC- suppressive effects and at later time points reduced their proliferative ability and viability." (PMID 30400822, 2018). "We have recently uncovered a key role for GSK3β, a known repressor of Wnt signaling, in the control of DC maturation, both at the level of melanoma cells and at the level of DC and their precursors." (PMID 30400822, 2018). "GSK3β inhibition also displayed anti-proliferative effects in other tumor entities, including leukemia, non-small cell lung cancer, melanoma, prostate, pancreatic, colon and renal cell carcinoma." (PMID 28800359, 2017). "Nicotinic acid hydroxamate inhibited melanin synthesis through the activation of the MEK/ERK and AKT/GSK3β signalling pathways in B16F10 melanoma cells." (PMID 28114924, 2017). "Intriguingly, we found that compared to control cells, CoQ0 treatment significantly decreased the expression of GSK3β in B16F10 melanoma cells." (PMID 26968952, 2016). "Here we describe a selective small molecule GSK3 inhibitor with potent in vitro activity against GSK3α and GSK3β with the ability to rapidly induce β-catenin dependent apoptosis in preclinical melanoma models." (PMID 25915038, 2015). "When a constitutively-active form of GSK3B was introduced into the melanoma cells, elevated levels of anti-apoptotic Bcl-2, Bcl-XL and survivin were detected while decreased levels of pro-apoptotic Noxa were observed." (PMID 24931005, 2014). "Recently, it has been shown that GSK-3β inhibition enhanced Sorafenib-induced apoptosis in melanoma cells." (PMID 19920820, 2009). "However, studies have shown that SERPINE2 promotes the metastasis of melanoma cells through the GSK-3β signaling pathway both in vitro and in vivo." (PMID 40356756, 2025). "In recent years, AKT/GSK3β/β-catenin signaling axis plays an important role in inhibiting the proliferation, invasion, migration, improving immunogenicity and reducing drug resistance of melanoma." (PMID 40495167, 2025). "Notably, the inactivation of GSK3β by Ser9 phosphorylation appears especially relevant for melanoma progression, as our findings reveal a significantly higher expression of p-GSK3β in melanoma specimens versus normal skin tissues." (PMID 41153674, 2025). "Inhibitors of GSK3β reduce the cell viability of BRAFi-resistant melanoma cell lines and thus may holds promise as a novel strategy to overcome BRAFi resistance and melanoma progression." (PMID 40184329, 2025). "Additionally, our examination showed that CDK2, GSK3B, CSNK2A1, and CDK1 were the significant kinases that target the greatest number of genes associated with metastatic-melanoma." (PMID 39820173, 2025). "Notably, the increase in p-GSK3β after CA treatment appears contradictory, given that the constitutive overexpression of p-GSK3β has been reported in melanoma tissues." (PMID 41153674, 2025). "This suggests that the activation of GSK-3β by ArcA may suppress the transcription or activity of these MMPs, thereby inhibiting the invasive capabilities of melanoma cells." (PMID 39948552, 2025). "Recent studies have also focused on the AKT/GSK3β pathway in melanoma." (PMID 40495167, 2025). "Although further investigation is needed, the data from this study provide substantial preclinical evidence supporting the potential of CA as an anti-melanoma therapeutic candidate, as a natural compound possessing both GSK3β-modulating and antioxidant properties." (PMID 41153674, 2025).
melanoma (continued). "Our data indicate that CA’s anti-melanoma efficacy could be attributed to this dual mechanism, whereby its antioxidant effects lower oxidative stress while concurrently facilitating GSK3β inactivation through phosphorylation." (PMID 41153674, 2025). "Our results align with findings and suggest that increased p-GSK3β (inactive form) expression in melanoma may contribute to tumor proliferation and progression." (PMID 41153674, 2025). "The Mann–Whitney U test indicated a median (interquartile range) of 0.3104 (0.1386~0.7502) for normal skin tissues and 1.1951 (0.9500~2.0602) for melanoma tissues with respect to p-GSK3β expression, with a statistically significant difference (p = 0.0009) between the two groups." (PMID 41153674, 2025). "Additionally, insufficient research exists regarding p-GSK3β expression levels in melanoma and the contribution of p-GSK3β to the initiation and progression of this malignancy." (PMID 41153674, 2025). "Inactivation of GSK3β through phosphorylation impairs its tumor suppressor roles, such as the regulation of β-catenin turnover and the control of cell cycle checkpoints, thus facilitating melanoma cell proliferation and promoting cell survival." (PMID 41153674, 2025). "Moreover, ALT inhibited GSK3β phosphorylation, and GSK3β has been indicated as a key ALT target in melanoma." (PMID 39684513, 2024). "In addition, fisetin is reported to bind to GSK-3β in melanoma cells and zebrafish and induce melanin production, which protects cells from ultraviolet rays in the current molecular docking study." (PMID 38139186, 2023). "ATL I inhibits cancer cell proliferation and induces apoptosis primarily by regulating the PI3K/Akt, JAK2/STAT3, TLR4/MyD88/NF-κB, Notch, and ERK/GSK3β signaling pathways to treat colon, gastric, lung, melanoma, ovarian, breast, bladder, leukemia, prostate, and cervical cancers." (PMID 37241729, 2023). "As a potential partner of eEF2K, we further analyzed whether eEF2K affects GSK3β phosphorylation in melanoma cells." (PMID 35347072, 2022). "In addition to MAPK signaling, we examined the depigmentation effect of ITA and DMI through PI3K/AKT/mTOR axis and GSK3β signaling in α-MSH-treated B16 melanoma cells." (PMID 35807430, 2022). "Taken together, our results demonstrated that nobiletin could induce ferroptosis by regulating the GSK3β-mediated Keap1/Nrf2/HO-1 signalling pathway in human melanoma cells." (PMID 35350242, 2022). "SERPINE2 could also promote melanoma metastasis through the glycogen synthesis kinase 3β (GSK-3β) signaling pathway." (PMID 35646893, 2022). "Subsequently, we further explored the potential mechanism of nobiletin-induced ferroptosis, and found that the expression level of glycogen synthase kinase 3β (GSK3β) in the skin tissue of patients with melanoma was significantly reduced compared to that in the skin of normal tissue." (PMID 35350242, 2022). "In addition, GSK3β inhibits CREB DNA binding activity while GSK3β inhibition promotes melanogenesis in B16 melanoma and normal human melanocytes." (PMID 35807430, 2022). "Our research revealed that GSK3β could mediate the regulation of the Keap1/Nrf2/HO-1 signalling pathway in nobiletin-treated melanoma cells." (PMID 35350242, 2022). "Based on the results, we speculated that RA could target ADAM17 to down-regulate its expression therefore inactivate ADAM17/EGFR/AKT/GSK3β axis, ultimately exerting anti-cancer effects on melanoma in vitro." (PMID 34224305, 2021). "In addition, rosmarinic acid enhanced cisplatin sensitivity of melanoma cells through mediating the ADAM17/EGFR/AKT/GSK3β axis." (PMID 34516354, 2021). "In addition, miR-769-5p has been involved in the oncogenesis and development of melanoma and can promote the proliferation of this malignancy by suppressing GSK3B." (PMID 32104700, 2020). "To determine whether the effect of melatonin on GSK-3β activation in SK-MEL-1 is shared with another melanoma cell line, we have included MEL-HO in the present study." (PMID 32674468, 2020).
melanoma (continued). "Furthermore, oridonin can prevent migration, invasion, cell adhesion, and TGF-β1-induced EMT in melanoma cells by inhibiting the activity of the PI3K/AKT/GSK‐3β signaling pathway." (PMID 31772677, 2019). "In addition, inhibition of NFATc2 by AM404 or zoledronic acid, or the GSK-3β inhibitor AR-014418 in association with the EZH2 inhibitor GSK126-induced significant anti-proliferative and pro-apoptotic effects on melanoma cell lines." (PMID 30710146, 2019). "We conclude that activation of GSK3β in the melanoma TME may simultaneously induce oncolysis and alleviate DC immune suppression, thereby enabling T cell activation and effective immune checkpoint blockade." (PMID 30400822, 2018). "GSK3 act as a tumor suppressor, increased GSK3β protein stability suppressed the Wnt/β-catenin pathway by phosphorylating beta catenin which leads in the ubiquitin/proteosome dependent degradation of β-catenin in melanoma cells." (PMID 26968952, 2016). "In order to determine whether GSK3 phosphorylation at the AKT site was decreased in the presence of riluzole, melanoma cells were incubated in the absence or presence of this agent for 4, 8 and 16 hours and GSK3β phosphorylation at the AKT site was analyzed." (PMID 23077590, 2012). "Interestingly, in melanoma, GSK-3β negatively regulates the stabilization of microphthalmia-associated transcription factor (MITF) as well as the Wnt/β-catenin and PI3K/AKT pathways, which promote cancer cell survival, proliferation, and resistance to apoptosis." (PMID 39948552, 2025). "Thus, IR-546 inhibited melanoma metastasis by inhibiting AKT/GSK3β/β-catenin in vitro." (PMID 40495167, 2025). "GSK-3β, a ubiquitously expressed serine/threonine kinase crucial for regulating glycogen synthesis, has emerged as a promising target for cancer treatment, including melanoma, owing to its role in key pathways modulating cell survival, proliferation, and drug resistance." (PMID 39948552, 2025). "Furthermore, in human melanoma A375 cells, rosmarinic acid treatment has been shown to reduce cell proliferation, migration, and melanin production by blocking glycogen synthase kinase-3β (GSK-3β)." (PMID 39684912, 2024). "Moreover, the GSK-3β-dependent Wnt pathway activation appears to reduce invasion and proliferation of melanoma cells in vitro and melanoma growth in xenografts in vivo by suppressing the expression of Sox10, which significantly increased in our nevi and melanoma samples." (PMID 38020918, 2023). "Interestingly, nobiletin could increase the expression of GSK3β and further inhibit the Keap1/Nrf2/HO-1 signaling pathway in human melanoma cells." (PMID 37767395, 2023). "Thus, the combination of tideglusib, a GSK3β inhibitor, with anti-PD-1 therapy could be a promising strategy for melanoma treatment." (PMID 35013211, 2022). "Consequently, the inhibition of AKT to activate GSK-3β in melanoma cells may result in the phosphorylation of Gle1A, which subsequently disassembled SGs, explaining the potential mechanism for the reduction of cell viability to ~50% observed at 72 h." (PMID 35897696, 2022). "Additionally, nobiletin increased GSK3β expression in melanoma cells." (PMID 35350242, 2022). "Therefore, we hypothesized that GSK3β may be involved in the mechanism of nobiletin-induced ferroptosis in melanoma cells." (PMID 35350242, 2022). "(2Z,3E)-6-bromoindirubine-3’-oxime (BIO) is a competitive GSK3β inhibitor at ATP binding site that proved to be efficient in a proliferation suppression and cancer cell number reduction in several cancer cell lines, such as breast, pancreatic, osteosarcoma, and melanoma lines." (PMID 32767962, 2021). "RA also down-regulated the expression level of ADAM17, EGFR, p-AKT and p-GSK3β in melanoma cells, suggesting that RA had the anti-cancer potential for melanoma treatment, and the underlying mechanism may be related to inhibiting the activation of ADAM17/EGFR/AKT/GSK3β axis." (PMID 34224305, 2021).